EPO (erythropoietin)
Diseases named in the same sentence as EPO in open-access papers (continued):
Sharing a sentence is not in itself a finding about the gene and the disease.
ischemia (78 papers, 2009 to 2026). A hypoperfusion of the BLOOD through an organ or tissue caused by a PATHOLOGIC CONSTRICTION or obstruction of its BLOOD VESSELS, or an absence of BLOOD CIRCULATION. "EPO treatment or increasing EPO signaling exhibit protective activity in animal models of liver ischemia-reperfusion injury associated with transplantation including bone marrow-derived mesenchymal stem cell transplantation in a mouse liver fibrosis model." (PMID 39996752, 2025). "Postischemic EPO treatment has led to increased erythropoiesis compensating the loss of red blood cells related to the ischemia model." (PMID 23497299, 2013). "This study was conducted to investigate neuroprotective effects of EPO treatment in rats subjected to global ischemia and sought at identifying if the treatment is associated with an improvement of sensorimotor and memory function." (PMID 23497299, 2013). "In gerbils, exogenous EPO administered directly to the brain was neuroprotective against brain ischemia, while infusion of soluble EpoR increased susceptibility to ischemia, and mild ischemia resulted in neural degeneration and impaired learning." (PMID 22567318, 2012). "Expression of EPOR and EPO production in mouse brain indicates EPO activity on the other side of the blood–brain barrier that contributes to neural cell proliferation, viability, and protection against ischemia and glutamate damage." (PMID 39996752, 2025). "In animal models, nitric oxide synthase (NOS) contributes to EPO activities including erythropoiesis, neuroprotection, and cardioprotection against ischemia-reperfusion injury." (PMID 38628440, 2024). "More specifically, EPO has been shown to decrease Cyt-C expression, playing a protective role against ischemia." (PMID 39338226, 2024). "They elevate lysosomal degradation, autophagy, and erythropoietin levels, while also preventing ischemia." (PMID 39519546, 2024). "Future studies with specific EPO-mimetic ligands are needed to elucidate the roles of EPORs in EPO-mediated neuroprotection under ischemia." (PMID 35250554, 2022). "Similar techniques had been used previously, such as overexpressing erythropoietin to treat ischemia." (PMID 33957983, 2021). "EPO treatment in adult animal models shows increase in newly generated interneurons and protection with EPO preconditioning prior to ischemia or middle cerebral artery occlusion." (PMID 34603036, 2021). "Astrocytes are the primary source of EPO in the brain and can promote the Production of EPO during ischemia." (PMID 34867201, 2021). "It is reported that the pretreatment with EPO or vitamin D3 prior to ischemia decreases the renal dysfunction-induced by IR damage and regulates glomerular filtration rate." (PMID 33262439, 2020). "Meloni and colleagues used erythropoietin (EPO) for PC induction at 8, 12, and 24 h before in-vitro model of ischemia and indicated that EPO preconditioning in neurons and PC12 cells protects them against harmful consequences of ischemia." (PMID 32641953, 2019). "In animal models of brain injury, preconditioning with EPO infusion is protective for ischemia or middle cerebral artery occlusion – induced learning disability and neuron death." (PMID 32038269, 2019). "Recently the effect of IS on HIF in response to ischemia was demonstrated as well as the key role of AhR in IS effect on EPO transcription under hypoxic condition." (PMID 28747155, 2017). "Taken together, these findings suggest that EPO promotes microglial polarization to the M2 phenotype 14 days after ischemia." (PMID 28840056, 2017). "Erythropoietin (Epo), a hypoxia induced hormone, has been shown to play a cardioprotective role in various experimental models of myocardial ischemia and ischemia-reperfusion via pleiotropic actions." (PMID 28109258, 2017).
ischemia (continued). "Although – to the best of our knowledge – the effects of EPO during HS have not been investigated in large animal models (i.e., swine, sheep, and dog), EPO has been shown to exert tissue protection in swine models of liver and spinal cord ischemia." (PMID 25365317, 2014). "EPO is reported to inhibit cell apoptosis and prevent ischemia-related damage in the brain, heart and retina." (PMID 25119659, 2014). "Conversely, preconditioning with EPO infusion to the lateral ventricle was observed to reduce ischemia-induced learning disability and ischemic death of CA1 neurons." (PMID 24918289, 2014). "In contrast, EPO treatment effectively prevents pan-necrosis of the penumbra tissue after focal ischemia." (PMID 23497299, 2013). "The aim of the present investigation was to study the effect of EPO treatment as a continuous intravenous administration in a model of global ischemia starting the treatment 20 minutes after reperfusion." (PMID 23497299, 2013). "In models of global ischemia, mimicking cardiac arrest, EPO is protective though only if applied prior to or 20 minutes after ischemia and only when administered through the intracerebroventricular (i.c.v.)route." (PMID 23497299, 2013). "Previous studies have shown that IN Neuro-EPO had neuroprotective effect in a similar ischemia animal model." (PMID 22701364, 2012). "Recently, EPO has been investigated extensively as a protective agent against the ischemia and cardiac injury." (PMID 24250553, 2012). "There are numerous studies showing the protection effect of EPO against ischemia especially in the cardiac and neurologic systems." (PMID 24250553, 2012). "HIF-1 is one of the factors activated in early ischemia that can induce vascular endothelial growth factor, erythropoietin, etc.." (PMID 21957487, 2011). "And exogenous EPO exerted neuroprotection through antioxidant activity after ischemia." (PMID 34336097, 2021). "These beneficial effects may be partly explained by the anti-inflammatory effects of EPO observed in various ischemia-reperfusion injury models." (PMID 32993806, 2020). "EPO administration before induced ischemia may be cardioprotective in terms of cardiac biomarkers in patients undergoing CABG with CPB." (PMID 33680042, 2020). "In addition, many protective effects of EPO, such as anti-apoptotic, antioxidant, angiogenic, and neuroprotective effects against ischemia have been demonstrated in cell cultures and animal models." (PMID 32405372, 2020). "In this context, experiments on a rodent model for transient middle cerebral artery occlusion (MCAO) suggest that beneficial effects of EPO treatment before ischemia onset can have a definite (if indirect) impact on the extent of ischemic edema and preservation of BBB function." (PMID 33312715, 2020). "Erythropoietin and erythropoietin receptor (EPOR) expression in the CNS is significantly increased after ischemia, hypoxia, and other stress conditions, suggesting that EPO might be an endogenous neuroprotective protein." (PMID 31084604, 2019). "The local magnetic field disturbances caused by the relatively high magnetic susceptibility of deoxygenated hemoglobin result in a lower signal intensity on the SWI map, which has been used to detect perilesional angiogenesis in sildenafil- or erythropoietin-treated rats after ischemia." (PMID 29854019, 2018). "Moreover, so-called “homing” (migration of circulating stem or progenitor cells into target tissue) of EPCs into the ischemic myocardium was observed, where ischemia is essential for the switching from a vascular “state” to EPO-induced neovascularization." (PMID 28703764, 2017). "Similarly, EPO-sustained release of gelatin hydrogen microspheres improved blood perfusion of ischemia limb in mice via increasing capillary and arteriolar densities mediated by upregulation of EPOR and the activation of AKT–eNOS–MMP-2 signaling pathway." (PMID 28703764, 2017).
ischemia (continued). "The authors declared that EPO might show neurotrophin-like properties in models of ischemia, trauma, epilepsy and MS and might therefore be a modulator in neurodegeneration." (PMID 28926646, 2017). "EPO-mediated prevention of blood–brain barrier disruption after ischemia might involve the storage of ECs, preservation of microvasculature integrity, and downregulation of VEGFR-1 and VEGFR-2 receptors." (PMID 28703764, 2017). "Moreover, EPO improves cardiac function by increasing blood flow and inhibiting myocyte apoptosis in ischemia rodent models." (PMID 26101463, 2015). "Furthermore, when administrated acutely after neonatal ischemia, EPO is not only neuroprotective but also stimulates angiogenesis and neurogenesis." (PMID 24755676, 2014). "Studies showed that EPO could reduce the cerebral ischemia, diminish the cerebral infarction area, and improve the renal function harmed by the ischemia/reperfusion." (PMID 23799989, 2013). "There are growing evidence indicating that the EPO administration could reduce ischemia and improve cardiovascular function after ischemia/reperfusion (I/R) injury." (PMID 24250553, 2012). "The administration of EPO before ischemia or at the onset of ischemia and/or reperfusion, could reduce or prevent the ischemia/reperfusion injury and improve the cardiac function recovery." (PMID 24250553, 2012). "Apoptosis requires the expression of effector proteins in the longer term; therefore, it could be interfered with at 18 hours after onset of ischemia by Neuro-molecules such as EPO, which can induce the expression of antiapoptotic proteins." (PMID 22701364, 2012). "Occlusion of the common carotid arteries in a gerbil induces a significant learning disability, which upon infusion of EPO into the lateral ventricles of these gerbils prevented the ischemia-induced learning disability and prevented the degeneration of hippocampal CA1 neurons." (PMID 21943500, 2011). "Interestingly, as compared with EPO, CsA therapy (group 4) offered similar protection of the brain against infarction/ischemia in the current study." (PMID 21864394, 2011). "Interestingly, previous studies have demonstrated that EPO therapy significantly reversed ischemia-related left ventricular dysfunction." (PMID 21864394, 2011). "In this study, we intended to demonstrate that G-CSF upregulates EPO expression via the induction of HIF-1α activity, and that the co-treatment of G-CSF and EPO synergistically enhances neural survival and angiogenesis in both primary cortical cultures and animal models of ischemia." (PMID 20404921, 2010). "Vitreous levels of EPO are higher in diabetic patients, suggesting that EPO may be produced as an endogenous neuroprotectant against ischemia." (PMID 19930719, 2009). "Notably, the strong neuroprotective effect of Erythropoietin exists in all stages of ischemia." (PMID 34867201, 2021). "Ischemia-induced growth arrest of astrocytes can be overridden by inhibition of regulator of G protein signaling 2 (RGS2) and treatment with cytokine erythropoietin (EPO), and cytokine-mediated induction of astrocyte survival early post-ischemia may contribute to neuroprotective effect." (PMID 32859229, 2020). "If this time frame of pharmacokinetics and the edema dynamics after cerebral infarction with the onset immediately after ischemia are taken into account, an even earlier time of application of EPO could possibly have led to a more pronounced neuroprotective effect." (PMID 33312715, 2020). "Although we could not directly evaluate local oxygen pressure, we speculate that improvement in cervical myelopathy is due to anti-apoptotic effects of EPO, preservation of motor neurons and axons, and improvement in local ischemia in the spinal cord with an increased oxygen supply." (PMID 31821342, 2019). "Erythropoietin may have neuroprotective potential after ischemia of the central nervous system." (PMID 29694605, 2018).
ischemia (continued). "Also reported to confer neuroprotective effects in ischemia is erythropoietin." (PMID 25904843, 2015). "Recent experimental studies revealed that the hematopoietic cytokine erythropoietin (EPO) had numerous tissue-protective effects apart from its action on erythropoiesis and that it prevented vascular and tissue damage caused by acute ischemia in the heart, brain and kidneys." (PMID 22954171, 2012). "The potential protective role of EPO in animal models of myocardial infarction has been assessed and beneficial effects have been observed regardless of whether EPO was administered before ischemia, at the onset of ischemia, or at reperfusion." (PMID 21943500, 2011). "Erythropoietin (EPO) improves the neurological outcome of animals after spinal cord ischemia (SCI) and its effects on ischemia-induced endoplasmic reticulum (ER) stress and the unfolded protein response (UPR) are considered possible molecular mechanisms." (PMID 36076955, 2022). "Following ischemia, HIF-1 and many of its target genes, such as erythropoietin (EPO) and VEGF, are increased and exert neuroprotective effects." (PMID 35281064, 2022). "Erythropoietin has been reported to increase neuronal expression of NDKA, conferring protection to cortical neurons in ischemia in vitro." (PMID 34638676, 2021). "SOCS3 expression is induced by JAK–STAT-activating cytokines including erythropoietin (EPO) and granulocyte colony-stimulating factor (G-CSF), and by myocardial insults, such as viral infection, pressure overload, or ischemia." (PMID 34292971, 2021). "The most frequently posited hypothesis attributes EPO-mediated neurological improvement to a greater cerebral oxygenation and subsequent mitigation of metabolic dysfunction, as observed both clinically and experimentally after ischemia and subarachnoid haemorrhage." (PMID 24344874, 2013). "In agreement with these previous reports, we observe significant upregulation of EPO and GLUT-3 in neurons after ischemia, which is suppressed by YC-1." (PMID 22110762, 2011). "Therefore, the cardiac oxygen-sensing VHL/HIF/EPO pathway may represent an endogenous cardioprotective response that works in tandem with other pathways (e.g. adenosine) to locally induce cardiomyocyte tolerance against ischemia or ischemia-reperfusion damage." (PMID 21811636, 2011). "It is believed that the retinal neovascularization in PDR results from ischemia and the consequent release of local hypoxic and pro-angiogenic factors such as VEGF, hypoxia-inducible factors and erythropoietin." (PMID 20976146, 2010). "EpoR expression extends beyond erythroid tissue and provides for potential EPO activity in non-erythroid tissues including EPO-protective response to injury or ischemia in brain, the cardiovascular system or skeletal muscle." (PMID 39284834, 2024). "The EPO interacts with erythropoietin receptor (EPOR) on neurons, which also has a variety of functions, especially in the protection of the brain after ischemia." (PMID 34867201, 2021). "Chlorogenic acid (and its metabolite dihydrocaffeic acid) administered either before or after ischemia reduced brain infarct volume, BBB damage and behavioral deficits in tMCAO rats by blunting MMP activation and increasing brain levels of EPO, HIF-1a and nerve growth factor (NGF)." (PMID 33383852, 2020). "Thus, EPO and VEGF apparently induce a systematic bias toward protection, repair and functional recovery in ischemia." (PMID 28880966, 2017). "Evidently, the EPO targeted detrimental mechanisms do not appear to contribute to selective and delayed neuronal death after global ischemia." (PMID 23497299, 2013). "Similarly, the protective effects of EPO compounds and MSC combinations are supported by a study which evaluated the effect of this combination on a rat model of ischemia." (PMID 23777889, 2013).
ischemia (continued). "Recent studies revealed that erythropoietin (EPO) has tissue-protective effects in the heart by increasing vascular endothelial growth factor (VEGF) expression and attenuating myocardial fibrosis in ischemia models." (PMID 22954171, 2012). "Erythropoietin (EPO), a hematopoietic cytokine, has been studied for its potential therapeutic effects in many neurodegenerative diseases, including Parkinson’s disease, AD, amyotrophic lateral sclerosis, spinal cord injury, brain ischemia, hypoxia, and hyperoxia." (PMID 36555679, 2022). "Similarly, EPO also reduced post-ischemic upregulated mRNA levels of IL-1β at both reperfusion timepoints, while the other cleavage product of inflammasomes, IL-18, did not appear to be affected by either ischemia or EPO administration." (PMID 34628598, 2022). "We show that EPO has no influence on neuronal survival and delayed neuronal cell death in the CA1 region in the hippocampus, cortex and striatum of rats subjected to ischemia but treatment significantly preserved memory function." (PMID 23497299, 2013). "Although EPO-mediated reduction of ischemia-induced inflammation has been proposed to occur via reducing neuronal death rather than by direct effects upon EpoR-expressing inflammatory cells, it remains unknown whether or not EPO can play a direct role in regulating inflammatory cell responses." (PMID 22567318, 2012).